YPEL4 (yippee like 4)
Synonyms: FLJ30213
Tractability: No criterion of Open Targets' tractability assessment is met for any kind of drug.
Gene: Protein-coding gene on chromosome 11 (57,645,087 to 57,649,944, reverse strand). Ensembl gene ENSG00000166793.
Subcellular location: Nucleus, nucleolus
Gene Ontology:
Cellular component: nucleolus
Genetic constraint (gnomAD): Loss-of-function variants: 5 observed, 17.17 expected, observed/expected ratio (o/e) 0.29, 90% interval 0.15 to 0.61. The upper end of that interval is the gene's LOEUF score, 0.61, which puts it in group 2 of 6, group 1 being the genes least tolerant of losing a copy. Missense variants: 127 observed, 166.6 expected, observed/expected ratio (o/e) 0.76, 90% interval 0.66 to 0.88. Synonymous variants: 61 observed, 57.69 expected, observed/expected ratio (o/e) 1.06, 90% interval 0.86 to 1.31.
Homologues: Orthologues: chimpanzee YPEL4 (100% identical), pig YPEL4 (100% identical), mouse Ypel4 (99% identical), rabbit YPEL4 (99% identical), rat Ypel4 (99% identical), guinea pig YPEL4 (98% identical), dog YPEL4 (78% identical), macaque YPEL4 (62% identical), Drosophila melanogaster l(2)37Bb (12% identical), Drosophila melanogaster CG3270 (9% identical), Caenorhabditis elegans M04B2.4 (9% identical). Paralogues in human: YPEL3 (78% identical), YPEL2 (76% identical), YPEL1 (74% identical), YPEL5 (32% identical), SARDH (31% identical), DMGDH (27% identical), AMT (22% identical), PDPR (20% identical), L2HGDH (15% identical), FOXRED1 (13% identical).
Diseases named in the same sentence as YPEL4 in open-access papers:
YPEL4 is named in the same sentence as 11 diseases in open-access papers, as found by Europe PMC text mining. Sharing a sentence is not in itself a finding about the gene and the disease. The quoted sentences say what the papers report.
pulmonary diseases (3 papers, 2018 to 2022). "Because of these interactions, it may be implied that YPEL4 has some involvement in pulmonary diseases linked to these pathways." (PMID 29892964, 2018). "YPEL4 may play an important role in asthma and other pulmonary diseases; thus, a series of new and meticulous studies aimed at determining the functional importance of YPEL4 and underlying signaling mechanisms in asthma and other pulmonary diseases have a very significant impact in the field." (PMID 29892964, 2018). "YPEL4 is part of a complex network of pathways involved in the development of many pulmonary diseases." (PMID 35321408, 2022). "Research on YPEL4 up to date also suggests that YPEL4 is a very important player in pulmonary diseases." (PMID 29892964, 2018). "YPEL4 is the part of a complex network of pathways involved in the development of many pulmonary diseases." (PMID 29892964, 2018). "For example, CLP1 is linked to cardiac muscle hypertrophy, YPEL4 has a role in pulmonary diseases, P2RX3 and ENSGALG00000007381 are involved in blood coagulation (Reactome; Uniprot), and SLC43A3 plays a possible important role in the repair and growth of the lung tissue under oxidative stress." (PMID 34021753, 2021). "YPEL4 may regulate the mitogen-activated protein kinase signaling pathway to mediate adrenal cell proliferation; this molecule is also likely to be a very important player in pulmonary diseases." (PMID 29892964, 2018).
asthma (2 papers, 2018 to 2025). "In our study, we observed changes in the expression of YPEL4 and related genes in asthmatic Meishan pigs, suggesting that YPEL4 may be involved in the cell proliferation and airway remodeling processes in asthma." (PMID 39858200, 2025). "It is possible that a specific inhibitor of MVP in terms of its interaction with YPEL4 would allow the MAPK pathway to simultaneously work with the PI3K pathway, suggesting that a specific MVP inhibitor would serve as a therapeutic target in asthma by promoting the activity of YPEL4." (PMID 29892964, 2018). "In terms of interactions with YPEL4, specific inhibitors of MVP may allow the MAPK pathway to work alongside the PI3K pathway simultaneously, suggesting that specific inhibitors of MVP may serve as therapeutic targets for asthma by promoting the activity of YPEL4." (PMID 39858200, 2025). "Future studies could focus on elucidating the exact role of YPEL4 in the pathogenesis of asthma." (PMID 39858200, 2025). "Mitochondrial reactive oxygen species, glutathione S-transferases, arginase 1 and RORC in immune regulation, the Notch pathway, YPEL4 in cell proliferation, and MARCKS in airway mucus secretion play roles in asthma pathogenesis." (PMID 39858200, 2025).
adrenocortical adenomas (1 paper, 2018). "It was reported that YPEL4 potentiates aldosterone production by increasing cell proliferation and found that YPEL4 expression in APA from patients was 2.4-fold higher compared with its expression in non-functioning adrenocortical adenomas (NF)." (PMID 29892964, 2018).
anemia (1 paper, 2021). A reduction in the number of red blood cells, the amount of hemoglobin, and/or the volume of packed red blood cells. "Due to the increased serum erythropoietin levels but lack of distinct phenotype in steady-state TED, we hypothesized that the kinetics of Ypel4-deficiency might be accentuated in a situation of induced anemia." (PMID 34354145, 2021). "Mice transplanted with Ypel4-null cells also failed to recover platelet counts at the same rate as controls, an expected side-effect to the lingering anemia since megakaryocytopenia occurs naturally during situations of hypoxia and active erythropoiesis." (PMID 34354145, 2021). "While lack of Ypel4 did not affect steady-state TED in the bone marrow or spleen, the anemia-recovering capacity of Ypel4-null cells was diminished." (PMID 34354145, 2021).
non-small cell lung carcinoma (1 paper, 2018). A group of at least three distinct histological types of lung cancer, including non-small cell squamous cell carcinoma, adenocarcinoma, and large cell carcinoma. "Because LRP is a protein encoded by MVP, which interacts with YPEL4, targeting YPEL4 may affect the interaction with LRP and pose as a potential treatment for non-small- cell lung cancer where LRP expression is higher." (PMID 29892964, 2018).
pneumonia (1 paper, 2022). An acute, acute and chronic, or chronic inflammation focally or diffusely affecting the lung parenchyma, caused by an infection in one or both of the lungs (by bacteria, viruses, fungi, or mycoplasma.). "The P. multocida serotype A strain may lead to downregulation of YPEL4 through TLRs, implying its involvement in pneumonia." (PMID 35321408, 2022).
polycythemia (1 paper, 2021). Abnormally high mass or concentration of red blood cells in the blood, either due to an increase in erythropoiesis or a decrease in plasma volume. "We demonstrated that Ypel4-deficiency leads to a secondary polycythemia in mice, with a slight increase in MCV that is accompanied by reticulocytosis." (PMID 34354145, 2021). "We showed that Ypel4-null mice displayed a secondary polycythemia due to an increased clearance of circulating RBCs." (PMID 34354145, 2021). "Our findings together provide evidence for a physiologically appropriate secondary polycythemia in the Ypel4-null mice." (PMID 34354145, 2021). "Taken together, our data demonstrates that the Ypel4-null mice disrupts transcription of the Ypel4 gene, and that this disruption leads to a macrocytic secondary polycythemia." (PMID 34354145, 2021). "We demonstrated that the Ypel4-null mice displayed a secondary polycythemia with macro- and reticulocytosis." (PMID 34354145, 2021).
cancer (2 papers, 2018 to 2023). A tumor composed of atypical neoplastic, often pleomorphic cells that invade other tissues. "This suggests that YPEL4 may be a possible therapeutic target for cancers as its function is thought to be involved with cell cycle processes due to its subcellular localization." (PMID 29892964, 2018).
tumor (1 paper, 2018). "This relationship of YPEL4 and molecular regulators that result in the positive correlation between YPEL4 and tumor diameter." (PMID 29892964, 2018). "Results also suggested a positive relationship between YPEL4 expression levels and tumor diameter in APA." (PMID 29892964, 2018). "They showed that YPEL4 is able to potentiate the production of aldosterone by increasing cell proliferation, as well as the positive correlation between YPEL4 expression and tumor diameter." (PMID 29892964, 2018).
YPEL4 also shares sentences with these, for which no sentence is quoted: adenoma (1 paper); lung carcinoma (1).